DNM2 (dynamin 2)
Diseases named in the same sentence as DNM2 in open-access papers (continued):
Sharing a sentence is not in itself a finding about the gene and the disease.
bladder cancer (6 papers, 2017 to 2025). "At the first stage of the current study, a bioinformatics analysis utilizing oncology databases was performed to investigate the importance of DNM2 in bladder cancer patients, as well as to understand the underlying mechanisms that contribute to tumor invasiveness." (PMID 39610009, 2024). "In this study, data mining, using the omics data, identified significant overexpression of the DNM2 gene in bladder cancer." (PMID 39610009, 2024). "Cytoplasmic DNM2 expression on the basis of the median H‐score (=285) as the cut‐off demonstrated that while 119 (56.9%) cases expressed low levels, 90 (43.1%) bladder cancer samples showed high levels of cytoplasmic expression of DNM2." (PMID 39610009, 2024). "Univariate and multivariate tests were utilized to investigate the importance of nuclear DNM2 expression and other clinicopathological features on survival outcomes in bladder cancer cases." (PMID 39610009, 2024). "This study, for the first time, aimed to evaluate the clinical and prognostic value of DNM2 in the pathophysiology of bladder cancer using bioinformatics analysis and experimental evaluation." (PMID 39610009, 2024). "Generally, the main aim of this study was to investigate the expression pattern and clinical significance of DNM2 in bladder cancer by applying available clinicopathological and follow‐up data obtained using IHC." (PMID 39610009, 2024). "Further, we identified significantly higher GEO gene expression of DNM2 in bladder cancer cases compared to normal bladder cases according to GENT2 (GPL570 platform) (p < 0.001)." (PMID 39610009, 2024). "Then, the immunohistochemical examination was conducted on 209 paraffin‐embedded bladder cancer samples to determine the expression pattern and clinical importance of DNM2." (PMID 39610009, 2024). "We also found that DNM2 is principally localized in the cytoplasm and membrane, and nuclear localization is observed in only 13% of the bladder cancer tissues, as confirmed by in silico analysis." (PMID 39610009, 2024). "Most remarkably, the univariate analysis data showed an association between nuclear DNM2 expression and worsened DSS in bladder cancer patients." (PMID 39610009, 2024). "In our review of the literature, the clinicopathological importance of DNM2 protein in the urinary system, including bladder cancers, has obtained much less consideration compared to its expression and function in other tumors." (PMID 39610009, 2024). "The findings of our IHC study exhibit a potential capacity of nuclear DNM2 in the prediction of poor clinicopathological outcomes in bladder cancer cases." (PMID 39610009, 2024). "In terms of intensity, membranous, cytoplasmic, and nucleus expressions of DNM2 were recognized in 182 (87.1%), 207 (99.0%), and 27 (12.9%) bladder cancer cases, respectively." (PMID 39610009, 2024). "The association between nuclear dynamin 2 (DNM2) expression and clinicopathological characteristics in bladder carcinoma (intensity of staining and H‐score)." (PMID 39610009, 2024). "Therefore, the nuclear DNM2 expression in bladder cancer supports the aggressive nature and higher stages of the tumor." (PMID 39610009, 2024). "The results of pathway and PPI network analyses indicated that DNM2 might be involved in the development of bladder cancer by influencing various signaling pathways." (PMID 39610009, 2024). "They suggested DNM2 as a potential risk factor for bladder cancer, however, without any information regarding expression pattern and prognosis." (PMID 39610009, 2024). "However, further studies should be done to elucidate the molecular mechanisms of the DNM2 nuclear localization and the following signaling pathways in bladder cancer." (PMID 39610009, 2024). "Our data mining findings demonstrated dysregulation of DNM2 gene expression in bladder cancer." (PMID 39610009, 2024).
bladder cancer (continued). "While the clinicopathological importance of DNM2 in the progression of some specific carcinomas has been well investigated, there is less research on the protein expression pattern in other tissues, like bladder cancer." (PMID 39610009, 2024). "Expression of dynamin 2 (DNM2) protein (intensity of staining, percentage of positive tumor cells, and H‐score) in bladder carcinoma tissue samples." (PMID 39610009, 2024). "Although there have been reports on the association of DNM2 and CAV1 expressions with cancer cell biology in bladder cancer, to our knowledge there has been no investigation into the significance of the expression profiles of DNM2 and CAV1 in OSCC." (PMID 40419438, 2025). "The Kaplan–Meier curve results displayed that bladder cancer cases with nuclear DNM2 expression had shorter DSS in comparison to cases without nuclear expression of DNM2 (Log Rank test, p = 0.028)." (PMID 39610009, 2024). "Further, ULCAN database demonstrated that protein expression of DNM2 was not assessed in bladder cancer tissues." (PMID 39610009, 2024).
Charcot-Marie-Tooth neuropathy (6 papers, 2012 to 2020). "Heterozygous pathogenic variants in DNM2 are associated with Charcot-Marie-Tooth neuropathy, a disorder of the peripheral nervous system (OMIM: 606482)." (PMID 32337068, 2020). "Among the hub proteins we identified, dynamin (DNM1) has been implicated in central nervous systems and DNM2 is involved in Charcot-Marie-Tooth neuropathy." (PMID 32041280, 2020). "More interestingly, mutations in dynamin 2 can also cause a dominant form of Charcot-Marie-Tooth neuropathy, and recently it was reported that mutations in another dynamin family member, dynamin 1, cause encephalopathy." (PMID 31680794, 2019).
neuroblastoma (6 papers, 2008 to 2025). Neuroblastoma (NB) is the most common solid, extracranial childhood tumor. "Interestingly, downregulation of DNM2 was linked to worse outcomes and older age in neuroblastoma patients." (PMID 40823088, 2025).
X-linked myotubular myopathy (6 papers, 2014 to 2025). A rare X-linked congenital myopathy characterized by numerous centrally placed nuclei on muscle biopsy and that presents at birth with marked weakness, hypotonia and respiratory failure. "In addition, upregulation of dynamin 2 was observed in skeletal muscles from mtm1–/y mice, which accurately models human X-linked myotubular myopathy (XLCNM), and heterozygous knockdown of dynamin 2 in the mtm1–/y mouse improves muscle pathology and function." (PMID 26035394, 2015).
acute lymphoblastic leukemia (4 papers, 2016 to 2024). Leukemia with an acute onset, characterized by the presence of lymphoblasts in the bone marrow and the peripheral blood. "Mutations in DNM2 are common in early T-cell precursor acute lymphoblastic leukemia." (PMID 27885263, 2016).
atherosclerosis (4 papers, 2020 to 2026). A disease characterized by the build-up of fatty material and calcium deposition in the arterial wall resulting in partial or complete occlusion of the arterial lumen. "In 46 upregulated OCRGs in MDs, upregulation of two regulators VAMP8 and SERPINA1 was shared between obese and atherosclerosis; and two upregulated regulators DNM2 and MTFP1 were shared between T2D and atherosclerosis." (PMID 34368262, 2021).
neutropenia (4 papers, 2011 to 2021). A decrease in the number of neutrophils found in the blood. "Defective packaging of cellular enzymes in granules (due to ELANE mutations) or cytoskeleton changes (WASP and dynamin 2 mutations) modify intracytoplasmic trafficking and result in neutropenia, possibly through an excess of apoptosis or defective maturation." (PMID 21595885, 2011). "To test whether Dnm2 wt/K562E mice display also signs of neutropenia, we evaluated blood samples of naïve Dnm2 wt/K562E mice and controls for CD4+ T cells, CD8+ T cells, B cells, neutrophils, inflammatory monocytes, macrophages and dendritic cells." (PMID 32129442, 2020). "Again, no major alterations indicative of a neutropenia were found, despite a statistically significant but unlikely biologically relevant very small change in B-cell numbers of infected Dnm2 wt/K562E spleens." (PMID 32129442, 2020).
oral squamous cell carcinoma (4 papers, 2015 to 2025). "Univariate and multivariate analyses of clinicopathological factors and the expression and aspects of DNM2 and CAV1 in relation to overall survival in patients with oral squamous cell carcinoma (n = 80)." (PMID 40419438, 2025). "We investigated the clinicopathological significance of the expression of two caveolae component proteins, dynamin‐2 (DNM2) and caveolin‐1 (CAV1), in primary tumors of patients with oral squamous cell carcinoma (OSCC)." (PMID 40419438, 2025).
cardiac arrhythmia (3 papers, 2014 to 2022). Any disturbances of the normal rhythmic beating of the heart or MYOCARDIAL CONTRACTION. "To determine the role of DNM2 in the occurrence and development of ischaemic arrhythmias, we further analysed DNM2 protein expression in the samples with different arrhythmia scores." (PMID 25092467, 2014). "We found that DNM2 protein expression was reduced in the ischaemic ventricular tissues and the reduction was in linearly correlated with the severity of the arrhythmia." (PMID 25092467, 2014). "Collectively, DNM2 and its multi-ion channel properties may be critical for establishing ischaemic cardiac arrhythmias." (PMID 25092467, 2014). "Furthermore, we found that pharmacological inhibition of DNM2 in isolated, intact rat hearts induces severe arrhythmias in vitro." (PMID 25092467, 2014). "Here, we have found that DNM2 plays an important role in acute ischaemic arrhythmias." (PMID 25092467, 2014). "Using Langendorff perfusion of isolated intact rat hearts with or without dynasore (15 μM), we found that the inhibition of DNM2 triggered arrhythmias, whereas arrhythmias were seldom observed in the hearts that were perfused with the vehicle DMSO." (PMID 25092467, 2014).
chronic myeloid leukemia (3 papers, 2021 to 2024). "In chronic myeloid leukemia cells, a complex formed by DNM2, Abelson helper integration site-1 (AHI-1) and the fusion oncogene BCR-ABL leads to activation of DNM2 through its phosphorylation by the BCR-ABL tyrosine kinase." (PMID 34294140, 2021). "Moreover, the direct enhancement of DNM2 activity results in autophagy initiation in chronic myeloid leukemia." (PMID 37608137, 2024).
epilepsy (3 papers, 2016 to 2022). A brain disorder characterized by episodes of abnormally increased neuronal discharge resulting in transient episodes of sensory or motor neurological dysfunction, or psychic dysfunction. "Additionally, a frameshift variant occurred de novo in a patient with epilepsy who did not demonstrate the phenotype related to DNM2-related diseases." (PMID 36619507, 2022).
heart failure (3 papers, 2014 to 2022). Inability of the heart to pump blood at an adequate rate to meet tissue metabolic requirements. "Our group first reported that DNM2 could mediate heart failure by modulating the Ca2+-dependent apoptotic death of cardiomyocytes 12, indicating that DNM2 plays an important role in cardiac disease." (PMID 25092467, 2014).
hereditary spastic paraplegia (3 papers, 2018 to 2024). Hereditary spastic paraplegias (HSP) comprise a genetically and clinically heterogeneous group of neurodegenerative disorders characterized by progressive spasticity and hyperreflexia of the lower limbs. "Autosomal‐dominant centronuclear myopathy results from mutations in the DNM2 gene which encodes Dynamin 2 (DNM2) also involved in rare cases of Charcot–Marie–Tooth disease and hereditary spastic paraplegia." (PMID 29246969, 2018).
HIV-1 infection (3 papers, 2017 to 2025). The type species of lentivirus and the etiologic agent of acquired immunodeficiency syndrome (AIDS). "Even if it is universally accepted that the large GTPase dynamin-2 is important during HIV-1 entry, its exact role during the first steps of HIV-1 infection is not well characterized." (PMID 28076788, 2017). "Though we did not test the effect of DNM2 knockdown on HIV-1 infection in CD4+ T cells, the increase in infection observed upon DNM2 knockdown in MDDCs in our study suggests cell-specific differences in the reliance on dynamin-2-mediated endocytosis." (PMID 40029073, 2025).
Infertility (3 papers, 2013 to 2016). "We found copy number differences in infertile dogs compared with fertile for genomic regions encompassing TEKT1, DNM2 and SOX8 genes, suggesting a role in infertility biology if deleted or duplicated with respect to reference copy number." (PMID 24373333, 2013).
microcytic anemia (3 papers, 2022 to 2023). Anemia in which the red blood cell volume is decreased. "The second Vps1 variant that we found to affect autophagy progression is I277G, which mimics the DNM2(V235G) mutation causing microcytic anemia." (PMID 37060997, 2023). "Because ubiquitous Dnm2 deletion or loss of function leads to microcytic anemia and embryonic lethality, we investigated whether Dnm2 was erroneously excised in Dnm2Plt–/– EBs." (PMID 36110936, 2022).
osteosarcoma (3 papers, 2021 to 2023). A usually aggressive malignant bone-forming mesenchymal neoplasm, predominantly affecting adolescents and young adults. "The osteosarcoma sample presented mutations involving ATRX, ERCC5, and COL1A1, while the leiomyosarcoma case showed EXT2, DNM2, and PSIP1 alterations." (PMID 36673024, 2023).
psoriasis (3 papers, 2019 to 2022). An autoimmune condition characterized by red, well-delineated plaques with silvery scales that are usually on the extensor surfaces and scalp. "DNM2 and ILF3 both have eQTL signals which match more closely with the TDMA locus than the psoriasis-specific locus upstream." (PMID 36323703, 2022).
T-cell acute lymphoblastic leukemia (3 papers, 2016 to 2021). Acute lymphoblastic leukemia of T-cell origin. "High DNM2 expression is also seen in subjects with T-cell ALL, but DNM2 expression in subjects with mutations is difficult to evaluate because of few subjects." (PMID 27885263, 2016).
acute myocardial infarction (2 papers, 2014 to 2024). Necrosis of the myocardium, as a result of interruption of the blood supply to the area. "To investigate the role of DNM2 in ischaemic cardiac arrhythmias, we first established a rat model of acute myocardial infarction via left anterior descending artery ligation." (PMID 25092467, 2014).
breast tumor (2 papers, 2020 to 2021). "Of note, MT1-MMP is overexpressed in 25% of triple-negative breast cancers, the type of aggressive and highly proliferative breast tumors in which DNM2 is also overexpressed." (PMID 34294140, 2021). "The expression of dynamin 2 was observed at different intensities in the cell membrane, cytoplasm, and nucleus in the breast tumor tissue samples." (PMID 33250680, 2020). "All these breast tumor tissue samples exhibit a higher DNM2 expression compared to normal tissues." (PMID 34294140, 2021). "Concomitant overexpression of both DNM2 and MT1-MMP may synergize to increase aggressiveness of breast tumors." (PMID 34294140, 2021).
demyelinating (2 papers, 2019 to 2025). "Induced Dnm2 deletion in adult SCs caused a rapidly-developing peripheral neuropathy with abundant demyelination." (PMID 30648534, 2019).
lymph node metastasis (2 papers, 2022). "Therefore, the expression of DNM2 can prevent tumor invasion and lymph node metastasis, and be used as a diagnosis indicator of 17 early cervical squamous cell carcinoma risk factors." (PMID 35178475, 2022).
Stroke (2 papers, 2025). Sudden impairment of blood flow to a part of the brain due to occlusion or rupture of an artery to the brain. "DNM2 mutations can affect blood cell formation and immune response regulation, including neutrophil migration, which could play a role in vascular inflammation—a key factor in stroke development." (PMID 39997650, 2025). "Moreover, DNM2 has been shown to influence endothelial cell function, which is important for maintaining vascular integrity and could, in theory, affect stroke risk." (PMID 39997650, 2025). "There is, however, indirect evidence that DNM2-related mechanisms could be involved in processes relevant to stroke." (PMID 39997650, 2025). "While there is growing interest in DNM2′s role in blood and hematopoietic systems, especially in clonal hematopoiesis and myelodysplastic syndromes, the direct link between DNM2 mutations and stroke is not yet well-established in the scientific literature." (PMID 39997650, 2025).
anemia (1 paper, 2022). A reduction in the number of red blood cells, the amount of hemoglobin, and/or the volume of packed red blood cells. "The data, therefore, excludes defective DNM2-dependent CD71-mediated transferrin uptake in EBs as the cause of the severe anemia, as has been described in mice expressing the Dnm2 loss-of-function mutation V235G ubiquitously." (PMID 36110936, 2022). "Together, the data suggested that DNM2 deletion in platelets and MKs combined with Mpl ubiquitous deletion induced an age-dependent lethal anemia in Mpl–/– Dnm2Plt–/– mice." (PMID 36110936, 2022).
bladder tumors (1 paper, 2024). "Since nuclear DNM2 expression was significantly associated with the recurrence of bladder tumor and poor DSS in the univariate test, these findings could be because of the short‐term follow‐up and small patient population." (PMID 39610009, 2024). "In conclusion, our data mining findings using various bioinformatics tools demonstrated dysregulation of DNM2 mRNA expression in bladder tumor compared to normal tissue samples adjacent to tumor and its involvement in different signaling pathways." (PMID 39610009, 2024). "GEPIA2 analysis by the TCGA database revealed a significant increase in DNM2 mRNA expression (|Log2FC| Cut‐off: 0.5) in 404 bladder tumor tissues in comparison with 19 normal bladder samples (p < 0.01)." (PMID 39610009, 2024). "In the bladder tumor tissues, DNM2 was expressed at varying intensities in the cell membrane, cytoplasm, and nucleus." (PMID 39610009, 2024). "Our IHC results represented remarkably higher DNM2 expression in bladder tumor samples compared to normal tissue samples adjacent to tumor." (PMID 39610009, 2024). "Furthermore, our study using the IHC method identified that DNM2 is overexpressed in bladder tumor tissues compared to normal tissue samples adjacent to tumor." (PMID 39610009, 2024). "We analyzed gene expression of DNM2 in bladder tumor by GEPIA2 and GENT2 platforms." (PMID 39610009, 2024). "In addition, to enhance our knowledge, future research should prioritize investigating the effects of DNM2 downregulation through siRNA‐mediated knockdown or CRISPR/Cas9‐mediated knockout in bladder tumors." (PMID 39610009, 2024). "Further, bladder tumor patients with nuclear DNM2 overexpression had shorter DSS, suggesting that nuclear expression of DNM2 may represent an important biological marker." (PMID 39610009, 2024).
Charcot-Marie-Tooth disease dominant intermediate B (1 paper, 2022). Autosomal dominant intermediate Charcot-Marie-Tooth disease type B is a rare hereditary motor and sensory neuropathy characterized by intermediate motor median nerve conduction velocities (usually between 25 and 45 m/s) and signs of both demyelination and axonal degeneration in nerve biopsies. "Mutations in DNM2 lead to a wide clinical spectrum including Centronuclear myopathy 1 (CMN1; OMIM: 160150), Lethal Congenital Contracture Syndrome 5 (LCCS5; OMIM: 615368); and Charcot-Marie-Tooth Disease, Dominant Intermediate B; (CMTDIB, OMIM: 606482)." (PMID 34740639, 2022).
colorectal adenocarcinoma (1 paper, 2025). The most common type of colorectal carcinoma. "It was found that elevated expression of RPL31, CCT2, RPL17, and NUP85, as well as downregulation of NUP98, CDC37, DNM2, and SNRPN resulted from corresponding μ-ASOs treatment, correlating with improved survival in colorectal adenocarcinoma patients according to the TCGA database." (PMID 41373892, 2025).